CXCL14 (C-X-C motif chemokine ligand 14)
Diseases named in the same sentence as CXCL14 in open-access papers (continued):
Sharing a sentence is not in itself a finding about the gene and the disease.
chordoma (1 paper, 2015). Chordomas are rare malignant tumors arising from embryonic remnants of the notochord in axial skeleton. "For example, CXCL13, CXCL14 and CLEC11A promoted inflammatory cell movement; the expression of these molecules in the endophytic chordomas was significantly higher than that in exophyticones." (PMID 25793716, 2015).
Cirrhosis (1 paper, 2024). A chronic disorder of the liver in which liver tissue becomes scarred and is partially replaced by regenerative nodules and fibrotic tissue resulting in loss of liver function. "Moreover, qRT‐PCR analysis of liver specimens from patients with cirrhosis and healthy donors demonstrated significantly elevated CXCL14 levels in cirrhotic individuals." (PMID 39358917, 2024).
co-infection (1 paper, 2014). "maxima co-infection compared with uninfected controls (ANXA1, HSP90B1, VEGFA, MTTP, TNFSF11B, TCF12, APP, and CXCL14)." (PMID 25504150, 2014).
coronary artery disease (1 paper, 2023). "This study investigated both platelet surface–associated and circulating levels of CXCL14 in patients with heart disease and associations of this chemokine with myocardial function and outcomes in patients with coronary artery disease (CAD)." (PMID 37255851, 2023). "•CXCL14 may be associated with recovery of myocardial function in coronary artery disease (CAD)." (PMID 37255851, 2023).
endometritis (1 paper, 2025). An acute or chronic, usually bacterial infectious process affecting the endometrium. "In conclusion, gavage of DI led to changes in genes related to uterine tissue, and the activation of CXCL14 might be associated with the enhancement of endometritis treatment by DI." (PMID 40227949, 2025). "However, the neutralization of CXCL14 eliminated the protective effect of guanosine on endometritis caused by E. coli, which was manifested by an increase in the histological score to 3.3 ± 0.52 and an elevation of the bacterial load to 97 033 ± 66 152 CFU per gram of the uterus." (PMID 40227949, 2025). "The RNA‐seq results highlighted an essential role of CXCL14 in the protective effect of guanosine against E. coli‐induced endometritis." (PMID 40227949, 2025). "Mechanistically, the protective effect of guanosine in endometritis is mediated by activating the expression of CXCL14 in uterine epithelial cells." (PMID 40227949, 2025). "Overall, our data suggested that the protective role of guanosine against endometritis is at least partially mediated by CXCL14." (PMID 40227949, 2025). "Furthermore, RNA sequencing (RNA‐seq) and immunohistochemical analysis demonstrated that the beneficial effects of DI on endometritis was attributed to the upregulation of CXCL14 expression in uterine epithelial cells." (PMID 40227949, 2025).
Ewing sarcoma (1 paper, 2025). A small round cell tumor that lacks morphologic, immunohistochemical, and electron microscopic evidence of neuroectodermal differentiation. "In Ewing sarcoma, there were 21 significant relationships, including IL-4/IL-1β (r2 = 0.55, p = 0.00048), IL-4/IL-8 (r2 = 0.68, p = 0.0000047), CXCL14/IL-15 (r2 = 0.61, p = 0.00013), and CXCL5/CXCL12 (r2 = 0.64, p = 0.000030)." (PMID 41008853, 2025).
fibrosarcoma (1 paper, 2019). A malignant mesenchymal fibroblastic neoplasm affecting the soft tissue and bone. "In terms of the first explanation, to investigate whether CXCL14 produced by mesenchymal-derived cells shows tumor-progressive effects, we employed mesenchyme-derived fibrosarcoma cells (MC57) and produced a stable cell line expressing CXCL14 (MC57-CXCL14) or control mock vector (MC57-MOCK)." (PMID 31014014, 2019).
fungal infection (1 paper, 2020). "We further found that NFATc2 inhibitor FK506 prevented the upregulation of chemokine CXCL14 induced by paclitaxel, which was in line with the previous finding that inhibition of NFAT signaling decreased the cytokine production during fungal infection." (PMID 33070779, 2020).
gastric adenocarcinoma (1 paper, 2016). "In gastric adenocarcinoma tissues, the unusually high methylation in CXCL14 promoter region contributes to the low expression levels of CXCL14 resulting in poor prognosis." (PMID 26733763, 2016).
Glucose intolerance (1 paper, 2022). Glucose intolerance (GI) can be defined as dysglycemia that comprises both prediabetes and diabetes. "CXCL14 is a chemokine secreted by BAT in response to thermogenic stimuli and M2 macrophage signaling, which can increase insulin action and mitigate systemic glucose intolerance." (PMID 35928901, 2022).
gynecological cancers (1 paper, 2024). "In addition to two genes (CXCL14 and NTN4) that were differentially expressed in the NR group compared with that in the R group, those included in the significant LR pair only in the NR group were associated with a good prognosis of ovarian or other gynecological cancers." (PMID 39135097, 2024).
heart failure (1 paper, 2024). Inability of the heart to pump blood at an adequate rate to meet tissue metabolic requirements. "Inhibition of CXCL14 expression has been postulated to promote heart failure, leading to increased fibrosis formation and dramatically impaired cardiac function." (PMID 38461325, 2024).
HIV-1 infection (1 paper, 2017). The type species of lentivirus and the etiologic agent of acquired immunodeficiency syndrome (AIDS). "We conclude that CXCL14 was unable to synergize with CXCL12 in the inhibition of HIV-1 infection, but, instead, substantially enhanced the infection of CD4+ target cells with both X4 and R5 HIV-1 particles." (PMID 28360196, 2017). "Inclusion of increasing concentrations of CXCL12 seemed to diminish the enhancement of X4 HIV-1 infection by CXCL14, which is in agreement with the critical role played by CXCR4 in this process." (PMID 28360196, 2017). "Here, we propose that CXCL14 stabilizes preferred conformations of CXCR4 for HIV-1 infection, possibly by promoting conformational changes in CXCR4 aggregates." (PMID 28360196, 2017). "Of note, CXCL14 did not synergize with CXCL12 in its HIV-1 suppressor activity (i.e., CXCL14 did not increase the potency of CXCL12 to inhibit HIV-1 infection)." (PMID 28360196, 2017). "Although more experiments are needed to clarify the exact mechanism, it is possible that CXCL14-mediated CXCR4 clustering may facilitate gp120 binding and, thus, X4 HIV-1 infection." (PMID 28360196, 2017).
Hypercalcemia (1 paper, 2020). An abnormally increased calcium concentration in the blood. "Hypercalcemia associated to granulomatous diseases is commonly reported, the potential pathogenic role of CXCL13 and CXCL14, both DEG in sarcoidosis and TB needs further investigation." (PMID 33276795, 2020).
infantile hemangioma (1 paper, 2018). "The chemokine CXCL-14 has been reported to be involved in the occurrence and development of infantile hemangioma." (PMID 29552284, 2018).
influenza infection (1 paper, 2023). "Interestingly, the expression of the Cxcl14 gene was higher in the lungs of influenza-infected NOD.SCID mice than in CB17.SCID mice." (PMID 37904257, 2023). "This raised the possibility that overexpression of CXCL14 may contribute to the suppression of lung inflammation following influenza infection in NOD.SCID mice." (PMID 37904257, 2023). "Both groups exhibited lower morbidity and mortality than the naive group that did not receive the AAV9 vector prior to IAV infection, suggesting that the pre-administration of the AAV9 vector conferred protection against lethal influenza infection, irrespective of Cxcl14 overexpression." (PMID 37904257, 2023).
intestinal cancer (1 paper, 2023). "Cochrane’s Q test did not provide evidence of heterogeneity between CCL14 (p = 0.768, p = 0.808), CCL22 (p = 0.502), CCL28 (p = 0.175), CXCL12 (p = 0.530) and CXCL14 (p = 0.534) and intestinal cancer." (PMID 38075694, 2023).
invasive carcinoma (1 paper, 2024). A carcinoma that is not confined to the epithelium, and has spread to the surrounding stroma. "Other differentially expressed transcripts include S100A7, LCN2, CXCL14, and CD207 (decreasing expression from premalignant lesions to invasive carcinoma), as well as IDO1, IL6, IL8, THBS1, and FN1 (increasing expression from premalignant lesions to invasive carcinoma)." (PMID 38706595, 2024).
lentivirus infection (1 paper, 2024). Virus diseases caused by the Lentivirus genus. "We also found that CXCL14 promotes the role of CCE in repairing the cornea through the wound healing assay in vitro and the corneal injury model with lentivirus infection in vivo." (PMID 38750454, 2024).
leptospirosis (1 paper, 2024). A contagious bacterial infection caused by spirochetes of the genus Leptospira. "It has been described that CXCL5 leads to CXCL3, CXCL1, and CXCL14 expression, which are all potent chemoattractants for neutrophils, indicating the occurrence of this mechanism on leptospirosis immune response." (PMID 39534703, 2024).
leukemia (1 paper, 2020). A malignant (clonal) hematologic disorder, involving hematopoietic stem cells and characterized by the presence of primitive or atypical myeloid or lymphoid cells in the bone marrow and the blood. "In human leukemia-derived cell lines and CD34+ hematopoietic progenitor cells, CXCL14 can compete with CXCL12 and thus inhibit CXCL12-CXCR4 signaling." (PMID 32708730, 2020).
mastitis (1 paper, 2016). Inflammation of breast tissue during lactation or postpartum due to an obstructed duct or infection. "A total of 28 genes (e.g., CXCL14, KIT, and SLC4A11) were suggested as the most promising candidates associated with S. aureus-induced mastitis for follow-up functional studies." (PMID 28083515, 2016). "Integrated analysis with QTL database further suggested 28 genes (e.g., CXCL14, KIT, and SLC4A11) as candidates of bovine mastitis." (PMID 28083515, 2016).
mesothelioma (1 paper, 2025). A usually malignant and aggressive neoplasm of the mesothelium which is often associated with exposure to asbestos. "Significantly higher levels of multiple chemokines were expressed in R- vs NR- mesotheliomas, namely CCL5, CCL16, CCL17, CCL19, CCL21, CCL25, and CXCL14 Benajmini-Hochberg adjusted P values < 0.05." (PMID 40691143, 2025).
metastatic cancer (1 paper, 2024). A carcinoma which has spread from the original site of growth to another anatomic site. "We compared the expression differences between metastatic cancer and primary cancer and found that, apart from a significant downregulation of CXCL14 and CCL28, as well as a significant upregulation of CXCL12 and CCL2, the expression levels of most chemokines did not achieve a twofold change." (PMID 39409185, 2024).
Myocardial fibrosis (1 paper, 2024). "CXCL14 exerts a synergistic effect with IRX1 to attenuate myocardial fibrosis and cardiomyocyte apoptosis." (PMID 38461325, 2024).
Myocardial necrosis (1 paper, 2023). Irreversible damage to heart tissue (myocardium) due to lack of oxygen after a heart attack (myocardial infarction). "However, platelet surface–associated CXCL14 correlated with the extent of platelet activation (CD62P) in patients with CAD, while plasma CXCL14 correlated with myocardial necrosis in patients with STEMI." (PMID 37255851, 2023). "Finally, in patients with STEMI, circulating CXCL14 levels correlated with the extent of myocardial necrosis (CK), suggesting that hypoxia may increase the expression of CXCL14 and influence the release of this chemokine during the acute phase response." (PMID 37255851, 2023).
Nephroblastoma (1 paper, 2022). An embryonal neoplasm characterized by the presence of epithelial, mesenchymal, and blastema components. "The expression of CX3CL1, CXCL14 and CXCL2 in nephroblastoma was significantly decreased." (PMID 35530333, 2022).
periodontitis (1 paper, 2020). An acute or chronic inflammatory process that affects the tissues that surround and support the teeth. "Comparing this cluster to the genes with differential methylation profiles in periodontitis-affected gingival tissue from the same patients, a similar effect was observed only in the case of CXCL14." (PMID 33256844, 2020).
pulmonary hypertension (1 paper, 2023). Increased pressure within the pulmonary circulation due to lung or heart disorder. "CXCL14 association with PAH has not been reported; however, CXCL14’s key role in inflammation and immune regulation may be a new therapeutic target for pulmonary hypertension." (PMID 36893166, 2023).
pyometra (1 paper, 2015). "COX-2 interacts directly with CXCL8/IL-8 and CXCL14, chemokines that were also overexpressed in pyometra." (PMID 26222498, 2015). "Overexpression of CXCL14 can contribute to inflammatory cell infiltration in pyometra due to its chemoattractive action in immune cells, like monocytes and natural killer cells." (PMID 26222498, 2015). "Both IL8 and CXCL14 are induced by COX2, thus selective COX-2 inhibitors could be an interesting treatment option in pyometra in terms of control the inflammatory response." (PMID 26222498, 2015).
sarcoma (1 paper, 2025). A usually aggressive malignant neoplasm of the soft tissue or bone. "It includes information on cytokines that have been poorly studied in sarcoma peripheral blood samples, such as IL-24, IL-27, CCL21, CXCL5, and CXCL14." (PMID 41008853, 2025). "Levels of IL-1β, IL-4, IL-6, CXCL5, CXCL12, CXCL14, MIF, IGF-1, TGFβ-1, and CCL21 were increased in one or more sarcoma cohorts compared with controls, and levels of IL-15 and IL-16 were significantly lower in one or more sarcoma cohorts compared to healthy controls." (PMID 41008853, 2025).
sarcopenia (1 paper, 2017). Progressive decline in muscle mass due to aging which results in decreased functional capacity of muscles. "Strikingly, we have observed that the impaired regenerative capacity in aging muscle is fully restored by Cxcl14 depletion, suggesting a potential therapeutic strategy against sarcopenia." (PMID 28775895, 2017).
squamous cell carcinoma (1 paper, 2022). A carcinoma arising from squamous epithelial cells. "There was a significant difference in plasma CXCL14 level among different histology subtypes (adenocarcinoma: 1647.88 pg/ml, squamous cell carcinoma: 2012.00 pg/ml, SCLC: 2886.00 pg/ml, other malignant types: 2776.21 pg/ml, P=0.009)." (PMID 35769715, 2022).
tongue tumour (1 paper, 2015). "In order to further investigate whether CXCL14 has a tumour-suppressing effect in vivo, we prepared and cloned CXCL14-expression vector-transfected and mock vector-transfected tongue tumour-derived cells." (PMID 25765541, 2015).
ulcerative colitis (1 paper, 2014). An inflammatory bowel disease involving the mucosal surface of the large intestine and rectum. "In ulcerative colitis (UC) 5 genes (CXCL14, CXCL5, GATA3, IL17C, and IL4R) were hypermethylated compared to healthy controls." (PMID 25526479, 2014).
tumor (222 papers, 2009 to 2026). "Clinical correlation analysis indicated that low CXCL14 expression in tumor tissues was significantly associated with presence of lymph node metastasis, tumor location, and advanced clinicopathological stage (p < 0.05)." (PMID 40943634, 2025). "On the other hand, CXCL14 produced from cancer-associated fibroblasts stimulates tumor growth and metastasis." (PMID 37848726, 2023). "These genes, including IL6, ICAM-1, and CXCL14, are associated with immune cell signaling, tumor progression, and metastasis, indicating that tumor cells induce a highly specific gene expression signature to enforce their tumorigenic properties in the TME." (PMID 36868311, 2023). "CXCL14-induced reduction of tumor growth and metastasis was diminished in T cell-deficient nude mice." (PMID 36012586, 2022). "In vitro and in vivo experiments show that higher CXCL14 expression in tumor cells is associated with decreased tumor growth and increased TIL." (PMID 35842899, 2022). "Many of these cell types promote tumor development, such as tumor-associated macrophages and tumor-associated fibroblasts which, for example, secrete the protumorigenic chemokine CXCL14." (PMID 35865015, 2022). "Cancer-associated fibroblasts- (CAFs-) derived CXCL14 functions as a stimulator to promote PC development and tumor growth." (PMID 35669852, 2022). "Genetic knockdown of FGF2 or genetic depletion of tumoral pericytes blocked CXCL14 expression and tumor-associated macrophage (TAM) infiltration." (PMID 35439170, 2022). "The reduced number of infiltrated NK cells in SCC‐25 tumour spheroid caused by sh‐CDX2‐1 was rescued by oe‐CXCL14 treatment." (PMID 33733587, 2021). "Ozawa et al17 reported that the anti‐tumour effect of gefitinib in HNSCC was associated with restoration of the gene expression of BRAK/CXCL14." (PMID 33733587, 2021). "The genes repressed in both GE1-HCC and GE2-HCC included those with supposed tumour-inhibiting activity, e.g. CXCL14, CCBE1, IGFBP1, RND3, BMP10 and COLEC10, which encode proteins involved in extracellular matrix remodelling, migration and the immune response." (PMID 33541355, 2021). "The tumor-suppressor activity of CXCL14 is more widely documented, with loss of CXCL14 expression by epigenetic silencing coinciding with tumor progression." (PMID 33123134, 2020). "S100a6 can be secreted from several tumor cell types, and has been implicated in regulation of cell cycle and CXCL14, a pro-inflammatory chemokine." (PMID 32785175, 2020). "The expression levels of CXCL9, CXCL10, CXCL11, CXCL12, and CXCL14 were associated with various tumor stages in HNSCC." (PMID 33489879, 2020). "GPR85, a candidate receptor for CXCL14, was found on the cell membranes of primary mammary fibroblasts obtained from benign breast mass (normal-associated fibroblasts, NAFs)." (PMID 31014014, 2019). "CAFs are known to secrete multiple growth factors and chemokines such as SDF-1, VEGF, FGF, and CXCL14 into the tumor microenvironment that promote the growth and invasion of the underlying tumor by triggering multiple pathways." (PMID 28186964, 2017). "CXCL14 chemo-attracts iDCs (immature dendritic cells), and causes the functional maturation of dendritic cells, which is critical for tumor immunity, by up-regulating the expression of dendritic cell maturation markers." (PMID 25760073, 2015). "The CXCL14 gene, whose copy number was significantly lower in HCCs compared with paired non-tumor tissues, encodes a chemokine that has been shown to play a pivotal role as a tumor suppressor in HCC." (PMID 25965583, 2015). "An example from the current study would be the association of higher levels of Cxcl14/CXCL14 being negatively associated with primary tumor burden in (TRAMP × NOD/ShiLtJ) F2 mice but positively correlated with disease recurrence in humans." (PMID 25411967, 2014).